MUC12 (mucin 12, cell surface associated)
Description:
Involved in epithelial cell protection, adhesion modulation, and signaling. May be involved in epithelial cell growth regulation. Stimulated by both cytokine TNF and TGF-beta in intestinal epithelium.
Synonyms: MUC-12; MUC-11; MUC11
Tractability: Antibody: its Gene Ontology location is reachable by antibodies, with high confidence; UniProt predicts a signal peptide or a membrane-spanning region.
Gene: Protein-coding gene on chromosome 7 (100,969,431 to 101,018,940, forward strand). Ensembl gene ENSG00000205277.
Subcellular location: Membrane
Pathways (Reactome):
Disease: Defective C1GALT1C1 causes TNPS; Defective GALNT12 causes CRCS1; Defective GALNT3 causes HFTC
Metabolism of proteins: O-linked glycosylation of mucins; Termination of O-glycan biosynthesis
Immune System: Dectin-2 family
Gene Ontology:
Biological process: regulation of cell growth
Cellular component: Golgi lumen; plasma membrane; membrane
Genetic constraint (gnomAD): Loss-of-function variants: 160 observed, 163.59 expected, observed/expected ratio (o/e) 0.98, 90% interval 0.86 to 1.12. The synonymous counts are far from expectation, so gnomAD's model fits this gene poorly and the ratio says little. Missense variants: 3,282 observed, 3,511.1 expected, observed/expected ratio (o/e) 0.93, 90% interval 0.91 to 0.96. Synonymous variants: 1,183 observed, 1,408.8 expected, observed/expected ratio (o/e) 0.84, 90% interval 0.8 to 0.88.
Homologues: Orthologues: dog LUZP4 (2% identical). Paralogues in human: SRRM2 (11% identical).